CRP (C-reactive protein)
Diseases named in the same sentence as CRP in open-access papers (continued):
Sharing a sentence is not in itself a finding about the gene and the disease.
Sepsis (continued). "In a ROC analysis to distinguish between patients with noninfectious SIRS and patients with sepsis/severe sepsis, IL-6, LBP and CRP had an AUC of 0.87, 0.86 and 0.84, respectively; compared to 0.75 for PCT." (PMID 19578505, 2008). "In a ROC analysis to distinguish between patients with noninfectious SIRS and patients with sepsis/severe sepsis, IL-6, LBP and CRP had an AUC of 0.87 (95% CI 0.78–0.96), 0.86 (95% CI 0.77–0.95) and 0.84 (95% CI 0.75–0.92), respectively." (PMID 16569262, 2006). "In our study PCT performed poorer than CRP, IL-6 and LBP in diagnosing infection and in discriminating between noninfectious SIRS and sepsis/severe sepsis." (PMID 16569262, 2006). "Our results indicated that variables including CVP, SOFA score, CRP, lactate, VIS, and RRI not reduced following 24h of ICU treatment could be utilized as predictive indicators for early detection of SA-AKI in sepsis patients." (PMID 39864312, 2025). "Furthermore, VDR levels have a negative correlation with Lac, CRP, APACHE II scores and SOFA scores in sepsis patients." (PMID 40370697, 2025). "First, an analysis was conducted on sepsis patients without CKD, controlling for various factors such as age, sex, stroke, WBC, ALB, TBIL, Scr, CO2CP, Lac, cTnI, FIB, CRP, MAP, ABX < 1 h, 24-h fluid balance, SOFA score, infection site, CKD, DM, CHF, COPD, VAD, MV, and CRRT." (PMID 40703277, 2025). "However, when identifying each dependent variable, not every inflammatory marker (WBCs, Neuts, Lymphs, CRP, and PCT) shows a significant relationship with LRTI, URTI, sepsis, and UTI, as indicated by their p-values." (PMID 40426796, 2025). "The use of both CRP and PCT to predict or support the diagnosis of negative-culture sepsis could theoretically increase the accuracy and rapidity of intervention." (PMID 40150637, 2025). "Additionally, THCQ appears to affect levels of WBC, PCT, CRP, IL-6, SAA, and PLT, with no severe adverse events observed, providing a valuable strategy for the treatment of sepsis." (PMID 40963685, 2025). "Additionally, the levels of Neu%, PCT, CRP, AST, DBiL, Cr, eGFR, and Ur in the sepsis group were significantly higher than in the non-sepsis group, while the levels of PLT and ALB were significantly lower (p < 0.05)." (PMID 39457503, 2024). "Compared to baseline information from patients with non-ARDS sepsis, patients with ARDS sepsis had a higher prevalence of smoking (P = 0.037), COPD disease (P = 0.005), and respiratory infections (P = 0.002), and elevated levels of CRP (P < 0.001) and PCT (P = 0.006)." (PMID 38238652, 2024). "Findings demonstrated that, within this period, the peak values of CRP, PCT, and WBC, when compared to non-septic instances, achieved area under the curve (AUC) values of 0.986, 0.921, and 0.360, respectively, effectively distinguishing verified sepsis cases." (PMID 39193501, 2024). "However, diagnosing early sepsis remains challenging due to the non-specific nature of traditional biomarkers like procalcitonin (PCT), C-reactive protein (CRP), and lactate." (PMID 39655134, 2024). "CRP ranked fourth in predicting patient survival with non-sepsis SIRS and similar considerations as for the SEPSIS cohort can be done, moreover, its importance in predicting survival of a non-sepsis SIRS cohort was already observed in animal studies." (PMID 38489347, 2024). "In addition, CRP and PCT were significantly elevated on admission in patients with sepsis compared with patients without sepsis." (PMID 38337856, 2024). "C-reactive protein (CRP) is a sensitive parameter for diagnosing non-systemic infections, whereas procalcitonin (PCT) appears to be a useful parameter for improving the diagnosis and monitoring of therapy in patients with sepsis and septic shock." (PMID 38474403, 2024). "However, no risk stratification was performed according to the severity of sepsis and no dynamic changes of CRP, PCT, and NLR during the course of sepsis were assessed." (PMID 37204560, 2024).
Sepsis (continued). "Current inflammatory biomarkers like serum CRP and PCT may be less valuable for discriminating between infectious and non-infectious sepsis, especially in chronic inflammatory diseases like ARDs." (PMID 37050995, 2023). "However, HBP does not perform better than other proposed sepsis biomarkers, such as procalcitonin (PCT) and C-reactive protein (CRP) in the trial." (PMID 36865384, 2023). "Thirdly, C-reactive protein measurement was not available in the bacterial sepsis group, nor was measurement of cytokines such as IL-1, IL-6 or TNF-α as these biomarkers are extensively studied in sepsis, regardless of etiology." (PMID 36982221, 2023). "However, when compared to CRP or PCT in ER patients, presepsin did not perform better in terms of diagnosing sepsis in this meta-analysis." (PMID 36941681, 2023). "Though negative predictive value was high for both CRP and PCT in the study, positive predictive value for mortality was high for both PCT1 and PCT3 signifying the better correlation with the worsening of sepsis." (PMID 36158418, 2022). "Furthermore, these two subgroups had significantly higher mean CRP values, leucocyte counts, LRINEC and modified LRINEC scores and rates of sepsis at admission than the subgroup without requirement of HBOT." (PMID 35932075, 2022). "Bivariate analysis revealed that age, absence of fever, high C-reactive protein (CRP) level on arrival, high SOFA-score, elevated lactate and the presence of sepsis or septic shock within 24 h from obtaining the first blood culture were all significantly associated with mortality." (PMID 36136283, 2022). "Yao and colleagues found that miR-25 displayed a superior diagnostic accuracy for sepsis compared to well-established markers such as CRP and PCT according to a ROC curve analysis in a well-characterized cohort of 70 patients with sepsis and 30 patients with noninfectious SIRS." (PMID 35907902, 2022). "On d0 the levels of CK-18, CRP and PCT were similar in patients with and without severe sepsis." (PMID 34255216, 2022). "Compared with neonatal pneumonia, our data revealed that neonates with sepsis had a higher CRP level and a lower ALB level, indicating that CRP and ALB may have the power in identifying sepsis from nonseptic neonates with pneumonia." (PMID 35873709, 2022). "Maximal CRP throughout hospitalization can occur at different time points and may reflect other pathophysiological processes superimposed on STEMI (e.g., sepsis, renal failure etc.)and thus may not reflect the mere response to STEMI." (PMID 35054095, 2022). "Next, compared to non-PICS survivors, survivors who had PICS 3 months after sepsis showed a higher detection rate of MRSA- and ESBL-producing bacteria and fungi in blood cultures, increased CRP levels, and a decreased GCS score on Day 7 after sepsis, which was an independent risk factor for PICS." (PMID 36142904, 2022). "Amongst them, procalcitonin (PCT), and C-reactive protein (CRP) are the most used, but unfortunately, they have not been shown to have good specificity and sensitivity and none of them has achieved the goals of a good biomarker for sepsis." (PMID 35329889, 2022). "Interestingly, altered arterial blood gases (O2 and carbon dioxide levels), sepsis severity (SOFA score), and biomarker of inflammation (C-reactive protein) did not correlate with respiratory effort." (PMID 34644374, 2021). "Moreover, the number of patients was not enough to evaluate presepsin for detecting severe sepsis and predicting the therapeutic course in comparison with PCT and CRP." (PMID 34641833, 2021). "Therefore, we further analyzed the course of routinely used pro-inflammatory markers (leukocytes, CRP, and PCT) as well as novel PSP in septic and non-septic patients across the three sepsis definitions." (PMID 34442346, 2021).
Sepsis (continued). "Despite the undoubted proved prognostic value of PCT and other sepsis biochemical markers, the observed early decrease in PCT and CRP blood levels was not significantly related with the survival group of patients in our research, although the PCT does seem to have a later useful prognostic value." (PMID 34430091, 2021). "However, children with sepsis had higher levels of HBP, CRP, IL-6, PCT, N%, and D-dimer than children without sepsis." (PMID 34778149, 2021). "From the available serum biomarkers for the diagnosis of sepsis, CRP, PCT, CD14, suPAR and other biomarkers showed good correlations for the diagnosis and treatment of sepsis, but their specificity and sensitivity are still not ideal for the diagnostic efficacy." (PMID 34565302, 2021). "Furthermore, some inflammatory markers were higher in the septic shock group compared to the sepsis group including PCT (2.6 [0.4–34.2] vs. 18.8 [7.0–66.5], p = 0.011), and IL-6 (309 vs. 658, p = 0.027), but not WBC or CRP." (PMID 35071235, 2021). "The purpose of our study to investigate the discriminative value of serum PCT, CRP, and WBC levels in distinguishing sepsis from infected without sepsis and no-infection, as well as to determine the optimal cut-off values of PCT and CRP for infection and sepsis in elderly critically ill patients." (PMID 34344141, 2021). "Ultimately, the comparison of results of CRP, PCO and PON1 confirm the hypothesis that in dogs with sepsis, oxidative phenomena are stronger than in dogs with non-septic inflammation, as already demonstrated for people." (PMID 34072427, 2021). "Hence, we conduct this prospective study to monitor some biomarkers (WBC, CRP, PCT, and sTREM-1) and body temperature (T) in AC patients with or without sepsis and control individuals." (PMID 32508526, 2020). "CRP and PCT levels were also assessed in vitreous humor and cerebrospinal fluid from the same groups (data not shown), reporting only vitreous humor PCT levels significantly higher in sepsis than in non-sepsis control cases." (PMID 33092081, 2020). "C-reactive protein (CRP), the clinically most important acute-phase protein, and interleukin-6 (IL-6) are both early biomarkers that can provide valuable information for distinguishing non-microbial SIRS from sepsis." (PMID 32912236, 2020). "We used cut-off values of 5 mg/l for CRP, since the reference range for a non-septic adult is < 5 mg/L and 0.5 ng/ml for PCT since this concentration is used in various algorithms for monitoring sepsis." (PMID 31419260, 2019). "Other inflammatory indicators, including complete blood counts, CRP and PCT, could also be useful in the timely diagnosis of sepsis, helping in the differential diagnosis of non-infectious diseases." (PMID 31703096, 2019). "C-reactive protein (CRP), interleukin-6 (IL-6), procalcitonin (PCT) and other biomarkers are also used to detect sepsis, but none of these can adequately predict the outcome of sepsis." (PMID 31568522, 2019). "However, similar to CRP and PCT, IL-6 concentrations were also elevated in non-septic disease states, limiting its specificity for the assessment of sepsis in patients with critical illness." (PMID 31569348, 2019). "In the non-sepsis sub-group, PCT levels were significantly higher in metastasis subjects compared to those without metastasis [0.25 ng/mL (0.07–1.76) vs. 0.09 ng/mL (0.03–0.54); p < 0.05], while levels of CRP and leukocyte were not significantly different." (PMID 29382396, 2018). "The RIPK3 levels in severe sepsis and septic shock group were markedly higher than those in sepsis group at various time points (all p < 0.05), and trends were remarkably similar for SOFA scores, CRP levels, and PCT among these groups but not RIPK1 levels and WBC counts." (PMID 29137405, 2017). "However, it did not predict blood culture positivity or severe sepsis and was inferior to PCT and CRP in predicting these latter two outcomes." (PMID 28845081, 2017).
Sepsis (continued). "Whereas CRP is non-specific and cannot be used to differentiate NEC from sepsis, it may be useful to determine disease progression; for example, a persistently elevated CRP may be indicative of treatment failure, whereas normalisation may indicate success." (PMID 27341512, 2016). "In our admitted febrile de-compensated cirrhotic patients, the lack of roles of serum CRP level, MELD score and APACH score in prediction svere sepsis might be due to different studied population contrast to other non-cirrhotic critically ill patients." (PMID 27861595, 2016). "Based on our results, most variables commonly affecting CRP and PCT values do not affect presepsin levels, which suggests that presepsin could be an effective sepsis marker." (PMID 26720209, 2015). "Similarly, in our study, CRP levels were significantly different between impaired renal function cases without SIRS, with sepsis, and with severe sepsis." (PMID 25407928, 2014). "In patients with infection, CRP levels were higher in cases with less severe infection, which was a significantly different result than the levels observed among patients without SIRS, with sepsis, and with severe sepsis." (PMID 25407928, 2014). "However, there is no other biomarker including CRP with such an extensive safety and efficacy record as PCT, notably in patients with LRTI and sepsis." (PMID 27029288, 2013). "However, PTX3 has not previously been compared with PCT in the case of sepsis patients, although in many papers PCT has been shown to be a better prognostic marker than CRP." (PMID 23341967, 2013). "According to the ROC curve analysis, the cut-offs points with the best sensitivity and specificity for CRP, DD, and PCT to discriminate at admission between sepsis and not sepsis (infection without sepsis or not infection) were 7.8 mg/dl, 1616 ng/ml, and 0.3 ng/ml, respectively." (PMID 24050481, 2013). "suPAR does not appear to be superior to other biomarkers, like CRP and PCT, in diagnosing sepsis." (PMID 22221662, 2012). "Therefore, our finding that LBP and CRP concentrations in nonsurvivors increased above that of survivors only from day 7 to day 14, but not in the first three days, may rather be due to the relatively good homogeneity of our study group regarding sepsis severity at study entry." (PMID 21901123, 2011). "Complications such as sepsis, infection, blood transfusion, prolonged intensive care unit treatment, and poor outcome were more frequent in patients with initially high PCT (>1 ng/ml), whereas increases of CRP showed no positive correlation." (PMID 16356205, 2006). "Although high PCT levels related to a higher frequency of developing sepsis, the initial PCT and CRP concentrations did not correlate with the severity of organ dysfunction, measured as maximum SOFA score values during the study period (r = 0.438, P < 0.01; not significant for multiple comparisons)." (PMID 16356205, 2006). "However, CRP is highly sensitive but non-specific, and while PCT offers greater specificity and disease-monitoring utility, its sensitivity can be limited in very early sepsis." (PMID 41597433, 2026). "In addition, biomarkers—such as C-reactive protein (CRP), procalcitonin (PCT), and plasma lactate—play an important role in the diagnosis and prognosis of sepsis, but they may not be sensitive enough to be an early and reliable marker on their own." (PMID 41315982, 2025). "PCT levels were not connected with IL-6, IL-12, or SOFA ratings in the sepsis group [r = 0.149, P = 0.176; r =−0.141, P = 0.202; r = 0.163, P = 0.138], but were positively correlated with WBC, CRP, and IL-8 [r = 0.430, P < 0.001; r = 0.285, P = 0.009; r = 0.258, P = 0.018]." (PMID 35937269, 2022).
Sepsis (continued). "In this study, sepsis was diagnosed based on the Sequential Organ Failure Assessment Score, and when multivariate analysis was performed, the odds ratios of PSEP and PCT were 0.0027 and 0.0024, respectively, which were statistically significant, whereas the odds ratio of CRP was not significant." (PMID 35666350, 2022). "Similarly in a different publication, although it concluded that sepsis cannot be differentiated from aseptic Systemic Inflammatory Response Syndrome (SIRS) based on CRP, in both cases, a rapid decrease of CRP, rather than initial concentration, was a good prognostic marker." (PMID 36290272, 2022). "Unlike CRP and WBC, which are usually measured to investigate the likelihood of disease and to inform decisions about antibiotics, lactate is a useful marker of severity in the ongoing management of sepsis, often requiring repeated measurements to investigate the trajectory." (PMID 35866444, 2022). "Therefore, CRP might be elevated in most AHDS patients due to widespread local inflammation of the entire intestinal tract, even without bacterial translocation or sepsis." (PMID 36713872, 2022). "Moreover, the measurement of PON1 and CRP at admission, but not of PCO, may predict the possible outcome of dogs with sepsis." (PMID 34072427, 2021). "Therefore, like CRP, PCT is not specific in early diagnosis of sepsis in burn patients." (PMID 33654698, 2021). "However, no research about whether CRP/Alb and PCT/Alb can evaluate the prognosis of patients with sepsis-induced AKI has been reported so far." (PMID 34141715, 2021). "Irrespective of the sepsis definition, PSP was the only marker to demonstrate a highly significant interaction between time and group (sepsis versus no sepsis) (p < 0.001) with a 3.3–5.5-fold increase within 72 h before the event of sepsis, whereas CRP, PCT, and WBC showed only mild undulations." (PMID 34442346, 2021). "Indeed, CRP and IL-6 levels both substantially differ between non-septic and septic patients, as well as between septic patients and patients with SIRS, thereby allowing for no sepsis, sepsis and SIRS to be differentiated." (PMID 32912236, 2020). "Among the three groups based on the REBA Sepsis-ID results, the CRP concentrations were significantly higher in the pathogen-positive group than in the contaminant-positive (p < 0.05) and negative groups (p < 0.05), and the AUROC value of CRP was 0.69 in predicting cases with pathogens." (PMID 32850901, 2020). "We analyzed a cohort of intra-abdominal origin septic patients (n = 35), who presented elevated levels of C-reactive protein (CRP) and procalcitonin (PCT) in their plasma 24 h after sepsis initiation, when compared to a control group of abdominal surgery patients that had not developed sepsis." (PMID 31221993, 2019). "However, we also found that CRP was not sensitive as PCT in accordance with complement C3 consumption, which may indicate the important role of complement in late stage of severe sepsis." (PMID 23091606, 2012). "The accuracy of DNI for differentiating between the presence and absence of severe sepsis/septic shock was higher than those of other laboratory markers (p < 0.001 for DNI vs. WBC; p = 0.002 for DNI vs. ANC; p = 0.02 for DNI vs. lactate; and p = 0.009 for DNI vs. CRP)." (PMID 22040292, 2011). "Indeed, TNF-α, IL-6, white cell blood count, C-reactive protein or procalcitonin did not correlate with serum ghrelin concentrations neither in all ICU-patients, nor in the subgroups of sepsis and non-sepsis patients in the clinical setting at admission to the Medical ICU (data not shown)." (PMID 20500817, 2010). "In addition, CIR-miRNAs in comparison to IL-6, CRP, PCT, and free Hb, generally showed more robust correlations with the APACHE II score, while IL-8 and Prdx-1 had significant positive correlation with the APACHE II score in non-infective SIRS, but not in sepsis." (PMID 29459855, 2017).
Sepsis (continued). "Furthermore, no significant decrease in the CRP, PCT, IL-6, leukocyte count, or NLR values was observed in the non-surviving group from Day-0 to Day-5; this ongoing inflammatory response may indicate an ineffective or delayed resolution of sepsis and correlate with disease severity and mortality." (PMID 41155833, 2025).